MTDH (metadherin)
Diseases named in the same sentence as MTDH in open-access papers (continued):
Sharing a sentence is not in itself a finding about the gene and the disease.
hepatocellular carcinoma (83 papers, 2010 to 2025). A malignant tumor that arises from hepatocytes. "Increased expression of MTDH is also implicated in hepatocellular carcinoma recurrence and metastasis which remains one of five most commonly diagnosed cancers worldwide, largely attributable to chronic viral hepatitis (HBV, HCV), and alcoholism." (PMID 31131259, 2019). "miR-302c negatively regulates expression of metadherin (MTDH) to impair EndMT associated with hepatocellular carcinoma." (PMID 27143978, 2016). "Other research has found that high levels of MTDH are associated with worse outcomes and higher chances of recurrence in various cancers, including breast, bladder, colon, and hepatocellular carcinoma, underscoring its role in cancer progression and patient prognosis." (PMID 41286067, 2025). "MTDH is overexpressed in hepatocellular carcinoma and is strongly associated with tumor metastasis." (PMID 36092898, 2022). "A recent study has shown that elevated MTDH levels are associated with drug resistance through the induction of multidrug resistance protein 1 (MDR1) expression in hepatocellular carcinoma (HCC)." (PMID 30791936, 2019). "S-palmitoylation of MTDH is verified in hepatocellular carcinoma (HCC) cells by the acyl resin-assisted capture method." (PMID 41318030, 2025). "It was shown that miRNA-30a can inhibit hepatocellular carcinoma cell proliferation by targeting the MTDH/PTEN/Akt pathway." (PMID 38200421, 2024). "The ASO targeting metadherin (MTDH), a gene can promote PD-L1 expression, was able to improve anti-PD-1 mAb therapy in hepatocellular cancer (HCC)." (PMID 37175900, 2023). "Studies demonstrate that MTDH is relevant in cancer cell invasion, since Matrigel invasion assays have shown that different cancer cells, such as hepatocellular carcinoma and glioma cells, display an increased invasive ability through MTDH overexpression." (PMID 36902125, 2023). "For instance, downregulation of MTDH expression is induced by miR-375 and results in reduced growth of hepatocellular carcinoma cells." (PMID 34893064, 2021). "In hepatocellular carcinoma, miR-302c inhibits tumor growth through metadherin, a factor that contributes to cell motility 4,53." (PMID 32467609, 2020). "EC-specific miR-302c inhibited metadherin expression, reduced EndMT, and suppressed tumor growth in hepatocellular carcinoma." (PMID 32467609, 2020). "Elevated expression of MTDH in hepatocellular carcinoma results in the up-regulation of multiple genes and signaling pathways such as the activation of ERK 42/44 and p38 Mitogen Activated Protein Kinase (MAPK) signaling pathway." (PMID 31131259, 2019). "MTDH is also associated with expression of the E-cadherin, β-catenin, snail, and N-cadherin epithelial-mesenchymal transition (EMT) markers in hepatocellular carcinoma cells." (PMID 31131259, 2019). "In hepatocellular carcinoma cells, MTDH is able to induce late SV40 factor leading to fluorouracil resistance as well as inducing the expression of multidrug resistance gene 1 and resulting in the development of doxorubicin resistance." (PMID 25684730, 2015). "The changes in EndMT markers after MTDH blockage is similar to the overexpression of miR-302c, which further confirms that miR-302c inhibits EndMT of ECs in hepatocellular carcinoma by directly targeting MTDH." (PMID 25027009, 2014). "Furthermore, miR-302c was observed to suppress EndMT in hepatocellular carcinoma by negatively regulating the expression of metadherin (MTDH)." (PMID 30076548, 2019). "Overexpression of MTDH has been observed in multiple types of cancer, including breast, esophageal, prostate, cervical and non-small-cell lung cancer, as well as neuroblastoma and hepatocellular carcinoma." (PMID 25684730, 2015).
hepatocellular carcinoma (continued). "More recently, MTDH has been found to connect with Wnt/β-catenin pathway in hepatocellular carcinoma cells through the activation of the Raf/MEK/MAPK branch of Ras signaling pathway, leading to β-catenin nuclear translocation and upregulation of different target gene expressions." (PMID 22768080, 2012). "Astrocyte elevated gene-1/Metadherin (AEG-1/MTDH) is a gene known for its overexpression in various cancers, including hepatocellular carcinoma (HCC)." (PMID 40282551, 2025). "Moreover, MTDH was directly regulated by miR-375 in both hepatocellular carcinoma and HNSCC." (PMID 25404787, 2014). "The MTDH gene is amplified in human hepatocellular carcinoma (HCC) patients, and the overexpression of MTDH has been identified in a high percentage of both hepatitis-B-virus- and hepatitis-C-virus-positive HCC cases, suggesting its key role in regulating HCC." (PMID 39351154, 2024). "The known mRNA interactors of miR-122 include PKM2, AKT1, MYC, TGFBR1, and SMAD4 in hepatocellular carcinoma, JNK, AP1, and caspases 3/8 in irritable bowel disease, and AKT, PI3K, PCNA, MTDH, PI3K, TRIM29, Bcl-W, CCNG1, and ALDO2 in CRC." (PMID 36499586, 2022). "Our previous study showed that CPEB3 could inhibit the metastasis of hepatocellular carcinoma (HCC) by inhibiting the expression of MTDH." (PMID 34930897, 2021). "There is also evidence of a functional link between MTDH and pro-survival mechanisms mediated by the lymphoid enhancer binding factor 1 (LEF-1) and GSK3β components of the Wnt/β-catenin pathway in chronic lymphocytic leukemia and hepatocellular carcinoma." (PMID 31131259, 2019). "The immunohistochemical analysis of 96 benign and 108 malignant lesions of the gallbladder revealed that the positive expression of erythropoietin-producing hepatoma-amplified sequence receptor A7 (EphA7) and AEG-1/MTDH is significantly higher in gallbladder adenocarcinoma than in benign lesions." (PMID 25009642, 2014). "Recent studies illuminated that MTDH can activate Wnt/β-catenin signaling pathway via ERK42/44 activation, which then leads to GSK3β phosphorylation, and thus facilitate nuclear translocation of β-catenin in hepatocellular carcinoma." (PMID 22768080, 2012). "Moreover, in hepatocellular carcinoma (HCC), PRMT5 and β-catenin may competitively interact with metadherin (MTDH), an oncoprotein, which regulates the Wnt pathway to promote HCC metastasis." (PMID 32961708, 2020).
glioma (60 papers, 2011 to 2025). A benign or malignant brain and spinal cord tumor that arises from glial cells (astrocytes, oligodendrocytes, ependymal cells). "Our previous study showed that MTDH expression was high in glioma tissues and cells and associated with glioma grades." (PMID 28107197, 2017). "Moreover, glioma cells can be sensitised to TMZ by silencing Metadherin (MTDH/AEG-1) which also attenuates M2-polarisation of glioma-associated microglia/macrophages." (PMID 36555253, 2022). "This study showed that MTDH and MYBL2 were overexpressed in gliomas, and knockdown of MTDH inhibited the expression of MYBL2." (PMID 36133745, 2022). "Further experiments showed that knockdown of MTDH inhibited the proliferation, migration, and invasion of glioma cells and promoted cell apoptosis." (PMID 36133745, 2022). "The TGF-β2/RSmads signaling pathway induced autophagy in gliomas, and has been reported to take place through AEG-1/MTDH activation, identified as a prominent oncogene." (PMID 35205289, 2022). "Along this line, it is of interest that miR-202 can downregulate the oncogene metadherin in gliomas." (PMID 35682549, 2022). "MTDH has been shown to be aberrantly expressed in glioma and has been shown to regulate EMT during cancer invasion." (PMID 36133745, 2022). "The present study showed that knockdown of MTDH inhibits glioma proliferation and migration and promotes apoptosis by downregulating MYBL2, which suggests that MTDH is a potential gene in clinical treatment of glioma." (PMID 36133745, 2022). "In brain tumors, miR-302c-3p can inhibit invasion and proliferation of glioma cells by targeting MTDH." (PMID 34151937, 2021). "Reports show that miR-30b-5p inhibits human colorectal cancer by targeting KRAS, PIK3CD and BCL2 and modulates glioma cell proliferation by directly targeting MTDH." (PMID 32586272, 2020). "MTDH is a multifunctional oncogene and has been demonstrated to be activated in many malignancies, including gastric cancer, prostate cancer and glioma." (PMID 30065618, 2018). "Based on analysis of TCGA database, we found that MTDH and mesenchymal markers are highly expressed in glioma, and MTDH expression level is positively correlated with mesenchymal marker Vimentin but negatively correlated with epithelial marker E-cadherin." (PMID 28107197, 2017). "In this study, we provided the first evidence that MTDH regulated glioma-related miR-130b expression." (PMID 28107197, 2017). "In conclusion, we demonstrate that in glioma cells MTDH acts as a co-activator for NF-kB to upregulate miR-130b expression, which in turn suppresses PTEN, PPP2CA and SMAD7 expression." (PMID 28107197, 2017). "MTDH overexpression increased glioma cells viability, while MTDH knockdown led to the opposite result." (PMID 28107197, 2017). "Here we demonstrate that MTDH was overexpressed in glioma tissues and cells and induced EMT-like change and invasion of glioma cells." (PMID 28107197, 2017). "Oncogenic AEG-1/MTDH is overexpressed in >90% of brain tumors and promotes gliomagenesis, particularly tumor growth and invasion, two primary characteristics of glioma." (PMID 25009642, 2014). "The cell migration and invasion of glioma cells U251 and U87 were detected after knockdown of MTDH." (PMID 36133745, 2022). "Subsequently, in order to study the role of MTDH in glioma, it was overexpressed and knocked down." (PMID 36133745, 2022). "The effect of knockdown of MTDH on the proliferation of glioma cells was then examined." (PMID 36133745, 2022). "This study is aimed at investigating the role of MTDH in glioma." (PMID 36133745, 2022). "In order to investigate whether the knockdown of MTDH would affect the proliferation and apoptosis of glioma cells, WB, CCK-8, and flow cytometry were subsequently performed." (PMID 36133745, 2022).
glioma (continued). "Moreover, this study has not established an animal glioma model, and a good animal model will provide some evidence for targeting MTDH in the treatment of glioma, which will be conducted in the following studies." (PMID 36133745, 2022). "Metadherin/astrocyte-elevated gene-1 (MTDH) is involved in the development of cancer, but its relationship with glioma remains unclear." (PMID 36133745, 2022). "This study is aimed at clarifying the role of MTDH in glioma." (PMID 36133745, 2022). "MiR‐30b regulated glioma cell proliferation by directly targeting MTDH." (PMID 32154657, 2020). "We hypothesized that MTDH might drive EMT-like change through regulating miRNA-ceRNAs network to promote glioma invasion." (PMID 28107197, 2017). "Our previous study showed that MTDH was highly expressed in glioma and could interact with NF-κB component p65 to promote staphylococcal nuclease domain containing 1 (SND1) expression." (PMID 28107197, 2017). "We further demonstrated that MTDH could modulate the expression of glioma-related miRNAs, especially miR-130b." (PMID 28107197, 2017). "In addition, glioma cells overexpressing MTDH exhibited enhanced mesenchymal characteristic and invasive capability, while glioma cells with MTDH depletion exhibited the reverse phenotypes." (PMID 28107197, 2017). "Here we demonstrate a novel mechanism of glioma invasion triggered by MTDH." (PMID 28107197, 2017). "To investigate whether MTDH regulates EMT-like process to drive glioma invasion, we modulated MTDH expression levels in GBM U87 cells." (PMID 28107197, 2017). "In this study, for the first time we revealed that MTDH could induce EMT-like change of glioma cells through regulating miRNA expression." (PMID 28107197, 2017). "AEG-1/MTDH may have a crucial function in the pathogenesis of glioma and may represent a viable potential target for malignant glioma therapy." (PMID 25009642, 2014). "Our results showed that knockdown of MTDH decreased the proliferation rate of glioma cells and increased the rate of apoptosis, while MYBL2 had the opposite effect, indicating that knockdown of MTDH could inhibit the proliferation and increase the apoptosis of glioma cells by downregulating MYBL2." (PMID 36133745, 2022). "However, it is still unclear how MTDH regulates glioma and its target gene." (PMID 36133745, 2022). "Whether MTDH positively regulates MYBL2 in glioma cells needs further study." (PMID 36133745, 2022). "Finally, cell migration and invasion assay results showed that knockdown of MTDH reduced the ability of glioma cells to invade and migrate, while MYBL2 was able to reverse this inhibition, indicating that knockdown of MTDH inhibited glioma cell migration and migration by downregulating MYBL2." (PMID 36133745, 2022). "Overexpression of MYBL2 could reverse the knockdown effects of MTDH in glioma cells." (PMID 36133745, 2022). "However, miR-26a induced autophagy in triple-negative breast cancer cells via the MTDH pathway and miR-26a induced autophagy in glioma cells via the DAPK1 pathway, suggesting that miR-26a might indirectly inhibit autophagy." (PMID 36522638, 2022). "Similarly, miR-136-5p could enhance glioma cell apoptosis via targeting MTDH (Metadherin) and Bcl-2." (PMID 32677950, 2020). "In this study, we explored the function of MTDH in glioma cells and found that MTDH and MYBL2 were highly expressed in glioma tissues based on the analysis of the GEPIA website." (PMID 36133745, 2022). "The results showed that MTDH and MYBL2 were overexpressed in glioma cells compared with normal cells." (PMID 36133745, 2022). "The knockdown of MTDH would inhibit the expression of MYBL2 through decreasing the expression of FoxM1 and further reduce glioma cell proliferation and cell migration and invasion." (PMID 36133745, 2022). "Out of the 13 signature genes, ATP6V1E1, EIF3D, ERCC1, GPNMB, MTDH, PCNA and NEDD9 have been reported to play crucial roles in various pathways and mechanism of glioma." (PMID 31632497, 2019).
glioma (continued). "Collectively, these results indicate that MTDH promotes EMT-like process and invasion of glioma cells." (PMID 28107197, 2017). "Taken together, we reveal a novel mechanism that MTDH induces EMT-like change and invasion of glioma via the regulation of miR-130b-ceRNAs, providing the first direct link between MTDH and miRNAs in cancer cells." (PMID 28107197, 2017). "MTDH promotes miR-130b expression and subsequently downregulates ceRNAs (PTEN, PPP2CA and SMAD7) to induce EMT-like process of glioma cells." (PMID 28107197, 2017). "Interestingly, MTDH could modulate the expression of a group of glioma-related miRNAs." (PMID 28107197, 2017). "We further confirmed high MTDH expression in large numbers of GBM tissue samples from The Cancer Genome Atlas (TCGA) database and in various glioma cell lines." (PMID 28107197, 2017). "Glioma-bearing rat are intracranially injected with 2 nM modified AED-1/MTDH siRNA-1 and AED-1/MTDH siRNA-2 seven days after initial tumor cell injection once every other day for two weeks (n = 5 per group)." (PMID 26909607, 2016). "This was verified in the present study, where knockdown of MTDH downregulates MYBL2, suggesting that it may play a role in the treatment of glioma." (PMID 36133745, 2022). "Moreover, we provided evidence that the stimulatory effects of MTDH on EMT-like process and invasion of glioma cells are mediated by miR-130b." (PMID 28107197, 2017). "Metadherin (MTDH), also known as astrocyte elevated gene 1 (AEG-1), is frequently up regulated and generally correlated with poor outcomes in cancers, such as colorectal cancer, liver cancer, lung cancer and glioma." (PMID 29088804, 2017). "Metadherin (MTDH) contributes to EMT in several cancers, but the role and mechanism of MTDH in EMT-like process of glioma remain unknown." (PMID 28107197, 2017). "Moreover, our previous study showed that MTDH interacted with p65 in the nucleus and promoted SND1 expression in glioma cells." (PMID 28107197, 2017). "Thus MTDH may regulate the expression of miR-130b-ceRNAs (PTEN/PPP2CA/SMAD7), which in turn regulate EMT-like process and glioma invasion." (PMID 28107197, 2017). "In keeping with the role of AEG-1/MTDH in a number of different aspects of malignancy, AEG-1/MTDH has been found to correlate with tumor progression and poor prognosis in a number of cancer types, including HCC and breast, prostate, glioma and esophageal cancer." (PMID 25009642, 2014). "Therefore, knocking down MTDH and targeting MYBL2 may provide new insights for glioma therapy." (PMID 36133745, 2022).